LINC02384 (long independently transcribed non-coding RNA 2384)
Gene: Long non-coding RNA gene on chromosome 12 (68,332,773 to 68,538,980, reverse strand). Ensembl gene ENSG00000251301.
Diseases named in the same sentence as LINC02384 in open-access papers:
LINC02384 is named in the same sentence as 3 diseases in open-access papers, as found by Europe PMC text mining. Sharing a sentence is not in itself a finding about the gene and the disease. The quoted sentences say what the papers report.
melanoma (1 paper, 2021). A malignant, usually aggressive tumor composed of atypical, neoplastic melanocytes. "LINC02446, LINC01857, and LINC02384 may stimulate melanoma progression by reducing tumor‐protecting miR.891a.5p and miR.203b.3p." (PMID 34159752, 2021).
LINC02384 also shares sentences with these, for which no sentence is quoted: cancer (1 paper); tumor (1).